HUWE1 (HECT, UBA and WWE domain containing E3 ubiquitin protein ligase 1)
Diseases named in the same sentence as HUWE1 in open-access papers (continued):
Sharing a sentence is not in itself a finding about the gene and the disease.
colorectal cancer (10 papers, 2011 to 2025). A primary or metastatic malignant neoplasm that affects the colon or rectum. "We identify a key role during colorectal tumour initiation for a gene called HUWE1 that is mutated in 7–15% of colorectal cancer cases." (PMID 28003334, 2017). "To determine the importance of HUWE1, we chose to examine its function in colorectal cancer, where it is mutated in up to 15 per cent of tumours." (PMID 28003334, 2017). "However, another study discovered that the deletion of HUWE1 in an APC-based mouse model of colorectal cancer accelerates tumorigenesis by increasing the levels of MYC and DNA damage accumulation." (PMID 36831013, 2023). "Treatment of these compounds inhibits MYC-dependent transactivation in colorectal cancer cells but not in stem cells or normal colon epithelial cells, and this effect is associated with the role of HUWE1 inhibition in stabilizing Miz1 and Miz1-mediated suppression of MYC target genes." (PMID 34178666, 2021). "Testing combination RNAi of RNF146 and HUWE1 in colorectal cancer cells may be informative." (PMID 21799911, 2011). "BI8622 and BI8626, identified through high-throughput screening, were found to inhibit the enzyme activity of HUWE1, repress MYC-dependent transactivation, and restrict the growth of colorectal cancer cells." (PMID 36831013, 2023). "Previous work established that small-molecule inhibitor of HUWE1 E3 ligase stabilizes MIZ1 and inhibits MYC-dependent transactivation in colorectal cancer cells." (PMID 36384931, 2022). "A recent high-throughput screening (HTS) has identified small molecule inhibitors of HUWE1, BI8622 and BI8626, that suppress transactivation of MYC target genes while increasing transrepression and the induction of apoptosis in colorectal cancer cells." (PMID 34178666, 2021). "For colorectal cancer, an exhaustive search revealed the FASTKD2, PANK1, and HUWE1 gene triple from the core to have the highest prognostic power (with respect to the training and filtration datasets)." (PMID 29402894, 2018). "Conversely, HUWE1 inhibition does not affect steady state levels of MYC in a model of colorectal cancer suggesting tissue specific regulation of MYC by HUWE1." (PMID 32523091, 2020). "Using high-throughputscreening, we identify small molecule inhibitors of HUWE1, which inhibit MYC-dependenttransactivation in colorectal cancer cells, but not in stem and normal colon epithelial cells.Inhibition of HUWE1 stabilizes MIZ1." (PMID 25253726, 2014). "As stem cells are proposed to be the cell of origin of colorectal cancer, the increased propensity of those lacking Huwe1 to undergo transformation may in part explain its tumour‐suppressive role." (PMID 28003334, 2017).
prostate carcinoma (9 papers, 2019 to 2025). A carcinoma that arises from epithelial cells of the prostate gland. "The expression of HectH9 (HUWE1) has been associated with disease progression in prostate cancer." (PMID 35937685, 2022). "In another in vitro study on prostate cancer cells, Fan and colleagues illuminated the role of Jumonji C domain-containing 1A (a histone demethylase) in inhibiting HUWE1-induced c-Myc degradation." (PMID 40034124, 2025). "On the other hand, R1 (CDCA7L/RAM2/JPO2) hinders the transcription of HUWE1, consequently enhancing the stability of c-Myc in prostate cancer cells." (PMID 40034124, 2025). "Interestingly, we detected an association between patient survival and gene expression of USP9X only, but not of HUWE1, BTRC, and FBXW7, even though all gene products are able to interact with Mcl-1, further emphasizing the role of the deubiquitinase in prostate cancer progression." (PMID 37173959, 2023).
multiple myeloma (6 papers, 2019 to 2022). "mRNA expression analysis indicates an increase in HUWE1 expression levels correlated with advanced stages of myeloma." (PMID 33116152, 2020). "We analysed the role of the E3 ubiquitin-protein ligase HUWE1 for pathobiology of multiple myeloma (MM), a still incurable blood cancer." (PMID 33116152, 2020). "Also, HUWE1 is frequently deregulated in multiple myeloma (MM) and targeting HUWE1 with the small molecule inhibitors in combination with lenalidomide results in synergistic growth inhibition in MM cells in vitro and in vivo." (PMID 34178666, 2021). "Therefore, we investigated if HUWE1 depletion may potentiate the anti-myeloma activity of melphalan." (PMID 33116152, 2020).
epilepsy (5 papers, 2019 to 2025). A brain disorder characterized by episodes of abnormally increased neuronal discharge resulting in transient episodes of sensory or motor neurological dysfunction, or psychic dysfunction. "Our findings are also consistent with prior clinical studies that showed genetic changes in HUWE1 are associated with neurodevelopmental disorders that have seizure/epilepsy as a comorbidity." (PMID 34797853, 2021). "Importantly, reported cases show epilepsy to be a comorbidity of XLID associated with missense mutations in HUWE1." (PMID 34797853, 2021). "Known cases note that epilepsy is a comorbidity with ID in patients harboring mutations in HUWE1." (PMID 34797853, 2021). "While seizure/epilepsy and autism are observed in some individuals with HUWE1 CNVs, the genetic links between HUWE1 and these neurodevelopmental conditions are much less clear and less consistent than ID." (PMID 32336296, 2020).
osteosarcoma (5 papers, 2015 to 2024). A usually aggressive malignant bone-forming mesenchymal neoplasm, predominantly affecting adolescents and young adults. "The miRNA 542-5p was found to be upregulated in osteosarcoma and was found to promote tumorigenesis by targeting HUWE1." (PMID 38164368, 2024). "HUWE1 was identified to be the direct target of miR-542-5p and the inhibition of HUWE1 promoted the proliferation of osteosarcoma in vitro and in vivo." (PMID 30467286, 2018). "To verify the involvement of HUWE1 in the miR-542-5p-induced promotion of osteosarcoma cell proliferation, we knocked down endogenous HUWE1 expression in osteosarcoma cells using a specific siRNA." (PMID 26498360, 2015). "HUWE1 was found to be a direct target of miR-542-5p in both osteosarcoma cell lines, and was negatively correlated with miR-542-5p levels in human osteosarcoma tissues." (PMID 26498360, 2015). "Knockdown of HUWE1 by siRNA in osteosarcoma cells transfected with miR-542-5p inhibitors attenuated the suppressive effects of miR-542-5p inhibitor on the proliferation of osteosarcoma cells." (PMID 26498360, 2015). "Taken together, our results indicated that miR-542-5p plays a critical role in the proliferation of osteosarcoma and targets HUWE1." (PMID 26498360, 2015). "Dual-luciferase reporter assays showed HUWE1 is a direct target of miR-542-5p in osteosarcoma." (PMID 26498360, 2015). "Our findings suggest miR-542-5p enhances the growth of osteosarcoma cells by targeting HUWE1 and may provide a potentially useful therapeutic target for treatment of osteosarcoma." (PMID 26498360, 2015). "Moreover, HUWE1 levels were negatively correlated with miR-542-5p expression in osteosarcoma tissues." (PMID 26498360, 2015). "Moreover, levels of miR-542-5p and HUWE1 are inversely correlated in osteosarcoma tissues." (PMID 26498360, 2015).
ovarian cancer (5 papers, 2018 to 2026). A primary or metastatic malignant neoplasm involving the ovary. "The clinical relevance of HUWE1 expression to ovarian cancer tumorigenesis was analyzed by using immunohistochemical staining with an anti-HUWE1 antibody and RNA analysis." (PMID 35937685, 2022). "Our results support the evidence that HUWE1 may be involved in ovarian cancer pathogenesis and is required for malignant transformation of ovarian epithelial cells." (PMID 35292711, 2022). "Three affected genes, HUWE1, PHF8 and KLF8, are related to breast or ovary cancers." (PMID 29558483, 2018). "A high expression level of HUWE1 was observed in the majority of tumors and was correlated with high mortality, suggesting that a high level of HUWE1 is a negative predictive and prognostic factor in ovarian cancer treated with chemotherapy." (PMID 35937685, 2022).
X-linked intellectual disability (5 papers, 2017 to 2022). An X-linked intellectual deficiency in which not enough information is known, reported or published to indicate whether a gene causes non-syndromic or syndromic presentations. "Missense mutations in HUWE1 are highly constrained (missense Z score = 8.87); both SNV and duplication Copy Number Variation involving HUWE1 are known causes of X-linked intellectual disability (ID; MIM: 309590)." (PMID 34950897, 2021). "Mutations in HUWE1 occur at moderate frequencies in cancers but are commonly associated with X-linked intellectual disability where they can lead to altered or enhanced activity." (PMID 32523091, 2020). "Mutations in the HECT, UBA and WWE domain-containing 1 (HUWE1) E3 ubiquitin ligase cause neurodevelopmental disorder X-linked intellectual disability (XLID)." (PMID 29118367, 2017).
B cell lymphomas (4 papers, 2012 to 2022). "Furthermore, high HUWE1 expression has been specifically linked to MYC driven B-cell lymphoma." (PMID 32523091, 2020).
lung adenocarcinoma (4 papers, 2016 to 2026). A carcinoma that arises from the lung and is characterized by the presence of malignant glandular epithelial cells. "This is especially intriguing in the context of our previous discovery of another member of the ubiquitin-proteasome pathway, HUWE1, as a plasma EV-associated marker of lung adenocarcinoma with good performance for distinguishing cases from controls." (PMID 32370304, 2020). "Here, by analysing human lung adenocarcinoma (LUAD) patient samples, we reveal that HUWE1 protein expression is commonly upregulated in LUAD tumours compared to normal adjacent lung tissue and that this increase is associated with tumour stage." (PMID 41942468, 2026). "They reported that SRGN, TPM3, THBS1, HUWE1, and CCDC18 were enriched in lung adenocarcinoma extracellular vesicles." (PMID 30646616, 2019).
thyroid cancer (4 papers, 2021 to 2023). "Ectopic HUWE1 expression in HUWE1 KD thyroid cancer cells sensitized this model to cisplatin and other genotoxins." (PMID 34065298, 2021). "HUWE1 expression was downregulated in thyroid cancer samples compared with control samples." (PMID 35937685, 2022).
virus infection (4 papers, 2018 to 2024). "Enrichment plots of interferon alpha response and interferon gamma response show significant upregulation in the Huwe1 KD group compared to control group during virus infection." (PMID 39034993, 2024). "High molecular weight of poly-ubiquitylated forms of Ascl1 were detected with the mock viral infection in the presence of MG132 but poly-ubiquitylated Ascl1 forms were severely reduced when Huwe1 was knocked down." (PMID 29545540, 2018). "Combined with previous studies, we have determined the following critical roles of HUWE1, UBR4, and UBR5 in virus infection." (PMID 38709105, 2024). "Taken together, the results demonstrated that HUWE1 and TRAF6 were downregulated during WSSV infection, leading to the increase in apoptosis and ROS levels and resisting the virus infection in the mud crab." (PMID 35107378, 2022). "Besides, silencing of HUWE1 or TRAF6 significantly suppressed the WSSV replication, indicating that these proteins could promote viral infection in the mud crab." (PMID 35107378, 2022). "In addition, it was found that HUWE1 interacts with HIV-1 Gag-Pol precursor protein via the IN domain and has a negative impact on the next round of viral infection by regulating early postentry events." (PMID 35107378, 2022).
Cognitive impairment (3 papers, 2013 to 2023). Abnormal cognition is characterized by deficits in thinking, reasoning, or remembering. "More importantly, dysfunction of the Huwe1 (a homolog of yeast Tom1) has been linked with multiple types of cancer and intellectual impairment, and Huwe1 has become a novel therapeutic target for the treatment of cancer." (PMID 37504517, 2023). "Whether HUWE1 is a relevant target of FMRP in regard to pathology, behavioral abnormalities or cognitive impairment in Fragile X syndrome remains unclear, but is certainly an interesting possibility given mounting evidence linking HUWE1 genetic changes to ID." (PMID 32336296, 2020). "Since all patients of the reported 12 families show only mild to moderate ID irrespective of the size of the duplication, HUWE1 appears to be the main gene underlying the cognitive deficits." (PMID 24303071, 2013).
gastric cancer (3 papers, 2022 to 2023). A primary or metastatic malignant neoplasm involving the stomach. "By comparing the expression level of HUWE1 in clinical gastric cancer patients and normal individuals, we showed that the expression level of HUWE1 was increased in tumor tissues." (PMID 35686089, 2022). "HUWE1 may become a potential target for the treatment of stomach cancer." (PMID 35686089, 2022). "In addition to DMD and HUWE1, we also found an association of DNAH family mutations with TMB, which was in accordance with findings that somatic mutation of the DNAH gene family was associated with higher TMB and better chemotherapy treatment response in gastric cancer patients." (PMID 37741340, 2023).
glioblastoma (3 papers, 2015 to 2022). The most malignant astrocytic tumor (WHO grade IV). "Furthermore, HUWE1 was identified as a master regulator of the balance between proliferation and differentiation during brain development, and HUWE1 knockout was associated with glioblastoma (GBM)." (PMID 35937685, 2022). "Proteasomal degradation of Pol β is however also mediated by C-terminal ubiquitination independent of HUWE1 and the Hsc70-interacting protein in LN428 glioblastoma cells, thereby further indicating context-specific relevance of HUWE1 on protein turnover." (PMID 34065298, 2021). "However, HUWE1 expression is reduced in glioblastoma and sarcoma." (PMID 35937685, 2022).
medulloblastoma (3 papers, 2018 to 2025). A malignant, invasive embryonal neoplasm arising from the cerebellum. "In SHH-type medulloblastoma, high expression of HUWE1 correlates with a better survival outcome, indicating that HUWE1 potentially serves as a tumor suppressor and a prognostic marker in brain tumors." (PMID 30176860, 2018).
skin tumors (3 papers, 2018 to 2023). "In another HUWE1 knockout mouse model, HUWE1 deletion causes increased severity of skin tumors, which were induced by carcinogens, 7,12-dimethylbenz-(a)-anthracene (DMBA) and 12-O-tetradecanoylphorbol-13-acetate (PMA)." (PMID 30176860, 2018).
autism (2 papers, 2020 to 2025). Persistent deficits in social interaction and communication and interaction as well as a markedly restricted repertoire of activity and interest as well as repetitive patterns of behavior. "This study also observed seizures and autism as comorbidities with non-syndromic ID in some individuals with HUWE1 mutations." (PMID 32336296, 2020). "De novo mutations in HUWE1 were found in individuals with schizophrenia and possibly autism." (PMID 32336296, 2020). "Thus, ID and autism could be comorbidities associated with mutations in HUWE1, or certain HUWE1 mutations could be risk factors for these conditions such that ID and autism can occur separately or together." (PMID 32336296, 2020).
bladder cancer (2 papers, 2021 to 2023). "A bladder cancer genome-wide CRISPR/Cas9 KO screen showed that HUWE1 was correlated with cisplatin sensitivity in bladder cancer; however, the underlying mechanism has not been elucidated." (PMID 37497216, 2023). "Integrating this mechanistic framework on HUWE1 as a sensitizer to platins with the recently discovered role of HUWE1 on cisplatin sensitivity in bladder cancer, support the high potential of HUWE1 to be used for such purposes." (PMID 34065298, 2021). "By addressing this topic, we aim to provide a mechanistic framework in support of our recent observations on HUWE1 in bladder cancer." (PMID 34065298, 2021).
brain tumors (2 papers, 2018 to 2024). "HUWE1 has also been identified as a potential therapeutic target in brain cancer due to its underexpression in brain tumors." (PMID 38879724, 2024). "HUWE1 is frequently overexpressed in solid tumors, but can be downregulated in brain tumors, suggesting that HUWE1 may possess differing cell-specific functions depending on the downstream targets of HUWE1." (PMID 30176860, 2018). "Therefore, a combination therapy downregulating both SHH signaling and Atoh1 by HUWE1 should be taken into consideration for brain tumors therapy, which may be a more promising therapeutic avenue." (PMID 30176860, 2018).
cervical cancer (2 papers, 2017 to 2019). A primary or metastatic malignant neoplasm involving the cervix. "In our cervical cancer data, the mutated genes involved in this pathway included FBXW7 (altered in 17%), HUWE1 (altered in 13%), and BIRC6 (altered in 9%)." (PMID 27998038, 2017).
craniosynostosis (2 papers, 2017 to 2020). Craniosynostosis is defined as the premature fusion of one or more cranial sutures leading to secondary distortion of skull shape resulting in skull deformities with a variable presentation. "For example, a small number of studies focused on craniosynostosis identified mutations in HUWE1, and also observed non-syndromic ID in these individuals." (PMID 32336296, 2020).